MCM4 (minichromosome maintenance complex component 4)
Diseases named in the same sentence as MCM4 in open-access papers (continued):
Sharing a sentence is not in itself a finding about the gene and the disease.
esophageal cancer (9 papers, 2012 to 2023). A primary or metastatic malignant neoplasm involving the esophagus. "As the member of Minichromosome maintenance protein family, MCM4 is high expressed in esophageal carcinomas and high histological grades BC." (PMID 37531195, 2023). "The increased level of MCM4 is related to the development and pathological stages of esophageal cancer." (PMID 34993142, 2021). "Values close to mean percentages of MCM4 (70%), MCM7 (70%) and Ki-67 (25%) expression had the best association between MCM4, MCM7 and Ki-67 expression and overall survival in esophageal carcinoma." (PMID 27476776, 2016). "Our study further confirmed that MCM4 expression correlated with cyclin E expression in esophageal carcinoma." (PMID 27476776, 2016). "In this study, we investigated CA9 expression in esophageal cancers and in precancerous lesions and explored the association of CA9 expression with prognostic factors and with stem cell and tumorigenesis-related markers including BMI1, cyclin E, ki67, MCM4 and MCM7 expression." (PMID 26156831, 2015). "In summary, our findings demonstrated the percentages of MCM4 and MCM7 expression significantly correlated with Ki-67, Bmi1, and cyclin E expression in esophageal carcinoma and precancerous lesions." (PMID 27476776, 2016). "In pairwise mean comparisons, the percentages of MCM4 and MCM7 expression was significantly greater than the percentages of Ki-67 expression in esophageal carcinoma and most of the precancerous lesions." (PMID 27476776, 2016). "MCM4 and MCM7 expression had similar distribution as Ki-67 and Bmi1 expression in esophageal carcinoma and pre-cancerous lesions." (PMID 27476776, 2016). "We also demonstrated the percentage of MCM4 and MCM7 expression to be significantly correlated with Ki-67, Bmi1, and cyclin E expression in esophageal carcinoma and precancerous lesions." (PMID 27476776, 2016). "The literature on MCM4 and MCM7 expression in esophageal cancer is limited." (PMID 27476776, 2016). "MCM4 and MCM7 may serve as more sensitive proliferation markers for evaluation of esophageal carcinoma and precancerous lesions." (PMID 27476776, 2016). "MCM4 is one of the highly conserved mini-chromosome maintenance proteins (MCM) that are essential for the initiation of eukaryotic genome replication and is highly expressed in esophageal cancer and cervical squamous cell carcinoma." (PMID 22559327, 2012). "While limited studies on MCM4 and MCM7 expression in esophageal carcinoma have been reported, none of the studies to the best of our knowledge investigated MCM4 and MCM7 expression by immunohistochemistry." (PMID 27476776, 2016).
Adrenal insufficiency (8 papers, 2012 to 2026). Insufficient production of steroid hormones (primarily cortisol) by the adrenal glands. "Finally, it is worth noting that severe POLA1 deficiency leads to hypogonadism, whereas MCM4 mutations lead to adrenal insufficiency, both states of reduced steroid hormone production." (PMID 31672938, 2019). "Intriguingly, patients with overactive NFKB2, responsible for the so-called noncanonical NF-κB pathway, may develop ectodermal dysplasia, a feature typical for XLPDR, as well as adrenal insufficiency, which is a feature of the MCM4 deficiency phenotype." (PMID 31672938, 2019). "Recently, two reports described mutations in the minichromosome maintenance complex component 4 (MCM4) that caused NK cell deficiency and adrenal insufficiency." (PMID 23240056, 2012). "Other components of the CMG helicase, including MCM4 and GINS1, have been linked to forms of primordial dwarfism similar to MGS, but they have been classified as clinically distinct due to the fact that they include immune deficiencies and/or adrenal insufficiency." (PMID 35603789, 2022). "While MCM4-null mice are not viable, mice expressing hypomorphic MCM4 suffered from adrenal insufficiency, although they were of normal size." (PMID 35603789, 2022). "Of note, several genes associated with adrenal insufficiency in humans were not differentially expressed during early development; namelyNNT,TXNRD2,AAAS,MCM4 andSGPL1." (PMID 28459107, 2017).
lymph node metastasis (6 papers, 2016 to 2025). "In the AJCC N2 subgroup—representing LUAD patients with advanced lymph node metastasis—high MCM4 expression was associated with an even higher risk of death, with an HR of 2.53." (PMID 40564876, 2025). "A multivariate Cox regression analysis of MCM4 showed that tumor size, lymph node metastasis and MCM4 high expression were also associated with OS in LUAD patients." (PMID 36291859, 2022). "Using univariate analysis we found a high percentage of MCM4 expression (>70%) to be significantly associated with lymph node metastasis and shorter survival in the adenocarcinoma group." (PMID 27476776, 2016). "The only significant association observed was between MCM4 expression and lymph node metastasis on univariate analysis." (PMID 27476776, 2016). "Only univariate analysis identified a significant association between MCM4 expression and lymph node metastasis in the adenocarcinoma group." (PMID 27476776, 2016). "MCM4 was significantly upregulated in LUAD tissues with lymph node metastasis, and in the N2 subgroup, patients with high MCM4 expression had markedly worse FPS outcomes (HR = 4.33, log-rank p = 7.6 × 10−6)." (PMID 40564876, 2025). "At the N0–N3 stage of lymph node metastasis, MCM4/6/7/10 showed the lowest expression in N3 tumors, which significantly correlated with patient prognosis." (PMID 36445337, 2022). "The multivariate Cox regression analysis of MCM4 indicated that tumor size (HR = 1.550, p = 0.012), lymph node metastasis (HR = 1.974, p < 0.0001) and high expression of MCM4 (HR = 1.459, p = 0.019) were closely related to OS in LUAD patients." (PMID 36291859, 2022). "There is evidence that high expression of MCM4 and MCM7 were associated with lymph node metastasis and shorter survival in EAC." (PMID 31380150, 2019). "Notably, MCM4 expression was significantly higher in tumors with advanced stage and lymph node metastasis, and it increased progressively from normal lung tissue to primary tumors and further to metastatic LUAD." (PMID 40564876, 2025). "In this research, the univariate Cox regression analysis of LINC00460 and MCM4 indicated that TNM stage, tumor size and lymph node metastasis were closely related to the OS of LUAD patients." (PMID 36291859, 2022). "In the univariate Cox regression analysis model of LINC00460 and MCM4, clinical prognostic factors such as TNM stage, tumor size and lymph node metastasis of LUAD patients were closely related to OS (p < 0.05)." (PMID 36291859, 2022). "Analytic results suggested that MCM4 over-expression was detected in patients with aggressive T stage, and MCM9 was over-expressed in patients with lymph node metastasis." (PMID 27695057, 2016).
pancreatic cancer (6 papers, 2008 to 2025). "It has also been shown the anti-pancreatic cancer activity of celastrol by up-regulating DDIT3 and ATF3 and down-regulating RRM2 and MCM4, however, the role of celastrol in anti-pancreatic cancer remains largely elusive." (PMID 38110764, 2023). "For example, in pancreatic cancer cells, Celastrol plays a cytotoxic role by regulating various gene expressions, mainly through ATF3/DDIT3 overexpression and RRM2/MCM4 downregulation." (PMID 36506508, 2022).
colorectal cancer (5 papers, 2019 to 2025). A primary or metastatic malignant neoplasm that affects the colon or rectum. "For example, MCM4 overexpression promotes cell proliferation and is associated with adverse outcomes in gliomas, endometrial cancer, hepatocellular carcinoma, and colorectal cancer." (PMID 40564876, 2025). "Abnormal expression of MCM4 has been observed in various cancers, including glioma, hepatocellular carcinoma, colorectal cancer, and uterine corpus endometrial carcinoma." (PMID 40564876, 2025). "Recent studies have shown that MCM4 is highly expressed in a variety of tumors including breast, ovarian, gastric, and colorectal cancers." (PMID 35719366, 2022).
endometrial cancer (5 papers, 2014 to 2025). Primary or metastatic malignant neoplasm involving the endometrium (mucous membrane that lines the endometrial cavity). "RT-qPCR and immunohistochemical results also showed that the expression of MCM4 was significantly up-regulated in endometrial cancer tissues." (PMID 35719366, 2022). "RT-qPCR and immunohistochemistry results also showed that MCM4 expression was significantly upregulated in endometrial cancer tissues and negatively correlated with patient prognosis (p < 0.05)." (PMID 35719366, 2022). "The relationship between MCM4 expression and prognosis of endometrial cancer patients was analyzed based on clinical characteristics, and Cox regression and nomogram prognostic models were used to verify the clinical significance of MCM4 in UCEC." (PMID 35719366, 2022). "In addition, we mainly analyzed the role of MCM4 in UCEC, confirmed that the expression and protein levels of MCM4 were significantly higher in endometrial cancer than in paracancerous tissues." (PMID 35719366, 2022). "Additionally, in endometrial cancer and skin cancer studies, it was found that MCM4 mutations may affect the interaction with MCM7, thereby disrupting the stability of the MCM4/6/7 complex." (PMID 33564675, 2021). "However, to date, the mechanism of action of MCM4 in endometrial cancer remains unclear." (PMID 35719366, 2022).
gastric cancer (5 papers, 2017 to 2023). A primary or metastatic malignant neoplasm involving the stomach. "In fact, we previously demonstrated the functional role of MCM4 in significantly increasing cell proliferative ability in MCM4 siRNA-transfected gastric cancer." (PMID 37737200, 2023). "We previously reported Minichromosome maintenance 4 (MCM4) overexpression in gastric cancer." (PMID 37737200, 2023). "We previously identified the minichromosome maintenance 4 (MCM4) gene from spheroid forming gastric cancer (GC) cells and reported its important role in GC progression." (PMID 37737200, 2023). "E2F1 may be crucial in the development of gastric cancer by influencing the cell cycle pathway and modulating its target gene MCM3, which may interact with MCM4, MCM5, and MCM7." (PMID 37594635, 2023).
hepatocellular carcinoma (5 papers, 2021 to 2025). A malignant tumor that arises from hepatocytes. "Increased expression of MCM4 is associated with poor prognosis in patients with hepatocellular carcinoma." (PMID 34993142, 2021). "Emerging evidence indicates that MCM4 is overexpressed in multiple malignancies, including hepatocellular carcinoma, and esophageal tumor." (PMID 41614789, 2025). "In conclusion, this study investigated the relationship between MCM4 and hepatocellular carcinoma prognosis." (PMID 34961841, 2021). "MCM4 has been reported to be a promising biomarker in the diagnosis and prognosis of several tumors, such as hepatocellular carcinoma." (PMID 34859821, 2021).
mammary adenocarcinomas (5 papers, 2009 to 2023). "MCM4 is involved in the MCM2-MCM7 complex essential for DNA replication licensing, and a MCM4 mutation (F345I) was reported to cause mammary adenocarcinomas in mice." (PMID 28506304, 2017). "This phenylalanine aligns in sequence with a phenylalanine of Mcm4 whose mutation, Mcm4(Chaos3), severely disrupts Mcm4:Mcm6 association and has been associated mammary adenocarcinoma." (PMID 26365238, 2015). "The Mcm4(Chaos3) mutation identified in mice (Mm) causes a point mutation of a conserved phenylalanine in Mcm4 (F345I), and female mice homozygous for this mutation often develop mammary adenocarcinoma." (PMID 26365238, 2015). "It is noteworthy in this context that a recent study exploiting a hypomorphic viable allele of Mcm4 was found to cause chromosomal instability and mammary adenocarcinomas in mice." (PMID 19240714, 2009). "In this study, we have shown that a mutation in MCM4 that predisposes mice to mammary adenocarcinomas also predisposes yeast to improved growth." (PMID 19636358, 2009). "A viable allele of Mcm4 caused chromosome instability and mammary adenocarcinomas in mice." (PMID 37491836, 2023).
non-small cell lung carcinoma (5 papers, 2013 to 2025). A group of at least three distinct histological types of lung cancer, including non-small cell squamous cell carcinoma, adenocarcinoma, and large cell carcinoma. "To further investigate the expression dynamics and clinical relevance of MCM4 in non-small-cell lung cancer (NSCLC), we analyzed multiple datasets and platforms." (PMID 40564876, 2025). "Elevated levels of Mcm4 were detected in non-small cell lung cancer (NSCLC) compared to neighboring normal bronchial epithelial cells." (PMID 29651420, 2018). "MCM4 was identified with the proliferation of non small cell lung cancer cells, but this gene may be responsible for the proliferation of EOC cells." (PMID 30970615, 2019).
acute myeloid leukemia (4 papers, 2019 to 2025). Acute myeloid leukemia (AML) is a group of neoplasms arising from precursor cells committed to the myeloid cell-line differentiation. "YTHDC1 realized oncogenic RNA splicing of tumor suppressor RBM4 during progression of cancer and was found to control the DNA replication regulator MCM4, which promotes proliferation and survival of acute myeloid leukemia cells." (PMID 40133252, 2025). "Conversely, we also observed that YTHDC1 modulates the expression of MCM2, MCM4, and MCM5 in acute myeloid leukemia (AML) cells by controlling their mRNA stability." (PMID 39414764, 2024). "Another confounding factor in these patients is that that GATA2 and MCM4—the two main genes involved in the origin of CNKD—could be relevant in carcinogenesis, including GATA2 mutations identified in families with predisposition to myelodysplastic syndrome and acute myeloid leukemia (MDS-AML)." (PMID 35203609, 2022).
cervical squamous cell carcinoma (4 papers, 2012 to 2018). A squamous cell carcinoma arising from the cervical epithelium. "MCM4 along with MCM3 has been reported to be highly expressed in cervical squamous cell carcinoma by immunochemistry." (PMID 30150654, 2018).
glioma (4 papers, 2022 to 2025). A benign or malignant brain and spinal cord tumor that arises from glial cells (astrocytes, oligodendrocytes, ependymal cells). "In glioma, high MCM4 expression facilitates tumor cell growth and is linked to reduced survival." (PMID 40564876, 2025). "The CCK8 assay showed that depletion of MCM4 significantly inhibits glioma cells’ proliferation ability." (PMID 36465369, 2022). "Collectively, these results demonstrate that MCM4 was highly expressed in glioma cell lines and significantly affected their proliferation and cell cycle." (PMID 36465369, 2022). "In the future, we will pay more attention to the function of MCM4 in tumor progression and tumor microenvironment regulation of glioma." (PMID 36465369, 2022). "In this finding, we found that MCM4 was highly expressed in glioma cell lines and significantly affected their proliferation and cell cycle." (PMID 36465369, 2022). "In summary, this finding confirmed that MCM4 is a potential target of precision therapy for patients with glioma." (PMID 36465369, 2022). "Furthermore, we will perform more in vivo and in vitro experiments to explore the function and the potential molecular mechanisms of MCM4 in tumor progression and tumor microenvironment regulation of glioma." (PMID 36465369, 2022). "However, the expression profiles, genetic alterations, clinicopathological parameters, diagnosis values, prognostic values, and immune functions of MCM4 glioma remain to be further elucidated." (PMID 36465369, 2022). "Therefore, we decided to explore the function of MCM4 in glioma." (PMID 36465369, 2022). "Overexpression of the genes whose transcripts act as potential targets fordysregulated miRNAs in the IDHmut and IDHwt groups is observed in moreaggressive glioma types: FKBP9 – CREB3L4, MCM4, MCM6, PSMB2, ARID1A, ARL4C, GRPEL2, and C9orf64." (PMID 39539523, 2024). "Univariate and multivariate analyses uncovered that MCM2, MCM4, MCM6, MCM7 expression, tumor grade, and age were independent factors that influence the clinical outcome of glioma patients." (PMID 36465369, 2022). "We also validated the expression of non-coding RNA that targets MCM4 and found that EXTL3-AS1was highly expressed, and miR-24-3p was down-regulated in glioma cell lines, respectively." (PMID 36465369, 2022). "Univariate and multivariate analyses revealed that MCM2, MCM4, MCM6, MCM7 expression and tumor grade, 1p/19q codeletion, primary therapy outcome, and age were independent factors that influenced the clinical outcome for glioma patients." (PMID 36465369, 2022). "Univariate and multivariate analyses revealed that MCM2, MCM4, MCM6, MCM7 expression and tumor grade, 1p/19q codeletion, primary therapy outcome, and age were independent factors correlated with poor clinical outcomes of glioma patients." (PMID 36465369, 2022). "Given that MCM4 expression was an independent factor affecting the prognosis of glioma patients and there is no previous study that reported the function of MCM4 in glioma." (PMID 36465369, 2022).
osteosarcoma (4 papers, 2013 to 2024). A usually aggressive malignant bone-forming mesenchymal neoplasm, predominantly affecting adolescents and young adults. "MCM4 has been detected as osteosarcoma driver gene as found to be over-represented in both copy number and expression profiles." (PMID 23874974, 2013). "According to our results, we also found that MCM4 played a core role in ONCOMINE, GEPIA, PROGNOSIS biomarker and KEGG analysis and the differential expression of MCM4 in osteosarcoma cell line was confirmed using qRT-PCR and western blot." (PMID 34239894, 2021).
ovarian carcinoma (4 papers, 2013 to 2023). A malignant neoplasm originating from the surface ovarian epithelium. "E2F2 induced upregulation of MCM4 expression in ovarian cancer, and was significantly associated with the poor prognosis of patients." (PMID 37817427, 2023). "We found that the mRNA expression levels of MCM4 were significantly upregulated in a variety of cancer tissues, including bladder, breast, cervical, and ovarian cancers." (PMID 35719366, 2022). "Microliposome maintenance (MCM) 2, MCM3, MCM4, MCM5, MCM6, and MCM7 are DNA replication regulators and are involved in the progression of multiple cancer types, but their role in ovarian cancer is still unclear." (PMID 34178669, 2021). "Analyses of eight unique datasets were performed for MCM2, MCM4, and MCM6 in ovarian cancer, and three were significant." (PMID 34178669, 2021).
prostate carcinoma (4 papers, 2021 to 2023). A carcinoma that arises from epithelial cells of the prostate gland. "Here, we report that MCM2, MCM3, MCM4, and MCM6 (MCM2/3/4/6) are elevated in human NEPC and high levels of MCM2/3/4/6 are associated with liver metastasis and poor survival in prostate cancer patients." (PMID 34172788, 2021). "MCM4, CENPI, and KNTC1 could serve as candidate diagnostic and prognostic biomarkers of castration-resistant prostate cancer and may provide potential preventive and therapeutic targets." (PMID 36035209, 2022). "The upregulated gene set included oncogenes such as PIK3CB, FGFRL1, and NCOA2; prostate cancer-related genes such as SPON2, PCAT4, and SCHLAP1; and cell cycle genes such as MKI67, MCM4, KIF4A, CENPF, and FLNB." (PMID 38067373, 2023).